HIF1A (hypoxia inducible factor 1 subunit alpha)
Diseases named in the same sentence as HIF1A in open-access papers (continued):
Sharing a sentence is not in itself a finding about the gene and the disease.
tumor (continued). "The expression of CA9 was predominantly found in perinecrotic tumor cells, but the positive expression of HIF-1α, nestin, and FOXM1 was widely distributed." (PMID 35785200, 2022). "PI3K inhibition by wortmannin further increased apoptosis following 12 Gy X‐ray irradiation, similar to the findings in Glut‐1 or HIF‐1α knockout tumours exposed to 12 Gy X‐ray irradiation." (PMID 35415942, 2022). "HIF1α promotes malignancy via effects on tumor angiogenesis, proliferation, epithelial to mesenchymal transition (EMT), stemness, and glucose metabolism." (PMID 35193955, 2022). "By activating AMPK and inhibiting mTOR and HIF-1α, Metformin in combination with 5-Fluorouracil increases the tumor response to chemotherapy by regulating the enzymes involved in the Warburg effect in human oral squamous cell carcinoma." (PMID 36568220, 2022). "Preclinical studies have suggested that metformin inhibits tumor angiogenesis by inhibiting the HIF-1a and VEGF-signaling pathways." (PMID 36008432, 2022). "HIF-1α expression is significantly correlated with aggressive tumor phenotype and poor prognosis in GC." (PMID 35681691, 2022). "In the current study, we demonstrated that an EBV‐encoded miRNA, EBV‐miR‐BART18‐3p, significantly promotes tumor growth and facilitates de novo lipogenesis in CRC by regulating the SIRT1/HIF1α/LDHA/FASN axis." (PMID 36307872, 2022). "In a hypoxic tumour environment, activation of hypoxia inducible factor 1α (HIF-1α) together with epigenetic reprogramming were described as the main contributors." (PMID 35887244, 2022). "Postoperative RT led to an overall decrease in any recurrence, however, there were still a higher number of recurrences in patients with a HIF-1α positive primary tumour." (PMID 35140341, 2022). "Elevated mROS activates hypoxia-inducible factor 1-alpha (HIF1α), which promotes tumour progression." (PMID 35490194, 2022). "The immunohistochemistry (IHC) method was applied to detect expressions of vascular endothelial growth factor (VEGF), hypoxia-inducible factor 1α (HIF-1α), and microvascular density-associated factor CD34 in tumor cells." (PMID 36046821, 2022). "Catalase in the core of the nanoplatform decomposed H2O2 to produce O2 in the tumor microenvironment to relieve hypoxia, directly reducing hypoxia‐inducible factor‐1α (HIF‐1α) expression and indirectly down‐regulating the expression of PD‐L1." (PMID 35652198, 2022). "PKM2 enzyme also increases the activity of STAT3 and HIF-1α and their downstream factors/genes promoting angiogenesis and tumor growth." (PMID 36419156, 2022). "It is also consistent to the observation that expression of full‐length HIF1α and PB1protein seems to be mutually exclusive in most ccRCC cell lines and in some primary tumours." (PMID 35672925, 2022). "In recent studies, HIF2α has been postulated to act as an oncoprotein, while HIF1α functions as a tumor suppressor in RCC." (PMID 36284084, 2022). "As hypoxia-induced ncRNA the miR-675-5p maintain hypoxic responses by controlling HIF1α mRNA stability and, in CRC, it modulates tumor progression by regulating HIF1α-induced EMT (epithelial-mesenchymal transition)." (PMID 35596172, 2022). "It was also observed that the stabilization of both HIF1α and HIF2α in VHLΔ/Δ mice promotes the clear cell phenotype of tumor cells while tumor cells from VHLΔ/ΔHIF1αΔ/Δ mice and VHLΔ/ΔHIF2αΔ/Δ mice had reduced frequency of the clear cell phenotype." (PMID 36040300, 2022). "This review discusses the underlying mechanisms by which hypoxia and HIFs (HIF1A and HIF2A) promote tumor immune escape, as well as the role of HIFs in cancer invasiveness, metastasis, and tumor chemoresistance." (PMID 35659268, 2022). "Deletion of HIF-1α decreased primary tumor formation and bone metastasis but increased the total tumor burden and lung metastasis." (PMID 36139678, 2022). "HIF‐1α has also been shown to upregulate checkpoint inhibitor programmed death‐ligand (PD‐L1), which inhibits effector T cell activity in tumours." (PMID 36495108, 2022).
tumor (continued). "The hypoxia tumor microenvironment (TME) induces the expression of the oncogene HIF-1α (hypoxia inducible factor-1α)." (PMID 35434271, 2022). "In situ immunofluorescence assay showed that ANGPTL4 was expressed synregionally with HIF-1α at high levels in mouse xenograft tumours." (PMID 36050447, 2022). "When an imbalance between oxygen supply and consumption, the hypoxia-inducible factor 1α (HIF-1α) was often induced to overexpress in the tumor cell." (PMID 35935500, 2022). "This study is the first to identify and validate FAM83A-AS1 as a metabolism-related lncRNA that facilitates tumor proliferation and stemness via the HIF-1α/ glycolysis axis." (PMID 35002507, 2022). "Metformin has also been found to significantly increase anti-tumor immunity by inhibiting HIF-1α activities." (PMID 35805044, 2022). "Secondly, the restraint of mTORC1 facilitated the reduction of the downstream HIF-1α expression, which contributed to attenuate tumors resistance to hypoxia and mitigated HIF-1α-induced tumor angiogenesis." (PMID 35413842, 2022). "In conclusion, swimming significantly attenuates tumor growth in CT-26 tumor-bearing mice by inhibiting tumor angiogenesis via the suppression of the HIF-1α/VEGFA pathway." (PMID 35291563, 2022). "G9a HMT has been reported to accumulate in a similar way to HIF-1α under hypoxic conditions and is attributed to the epigenetic silencing of many tumor suppressors involved in the cell cycle, apoptosis, DNA repair, angiogenesis, and metastasis." (PMID 36231060, 2022). "The tumor cells in cluster 1 adapted to hypoxia and survived, which expressed genes in the HIF-1α pathway and hypermetabolic pathway." (PMID 36685583, 2022). "In the context of ccRCC, HIF2α plays a major tumor-promoting role whereas HIF1α appears to function as a tumor suppressor." (PMID 35159281, 2022). "Metformin-activated AMPK/mTOR signal transduction pathway can reduce the expression and stability of hypoxia-inducible factor-1α (HIF-1α) in tumor cells." (PMID 36397350, 2022). "The hypoxic condition of the tumor cell microenvironment can induce activation of HIF-1α, stimulating the transcription of various growth factors, cytokines, and extracellular matrix (ECM) remodelers to create vasculature." (PMID 36289931, 2022). "HIF1α is a crucial factor that regulates cancer cell behavior under hypoxic conditions in the tumor microenvironment." (PMID 35941273, 2022). "Glucose metabolic reprogramming by converting glycolysis to OXPHOS or tumor cell metabolic plasticity has been noticed in several types of tumor cells and is regulated by the HIF-1α and AMPK signaling." (PMID 35101076, 2022). "Hypoxia inducible factor-1α (HIF-1α) is a key regulator of metabolic reprogramming in tumor cells, and estrogen-related receptor α (ERRα) plays a key role in regulating cellular energy metabolism." (PMID 35800058, 2022). "S100A4(+)/HIF-1α(−) tumor cells are subsequently recruited to, and migrate along, preexisting vessels in the presence of extracellular VEGF released by S100A4(+)/HIF-1α(+) GBM cells." (PMID 35392912, 2022). "Curcumin is a natural bioactive compound isolated from the rhizomes of Curcuma longa L., that exhibits great anti-tumor activity through the reduction of the levels of hypoxia factor 1 (HIF-1α) generated during PDT." (PMID 36338755, 2022). "HIF1A positively regulates PD-L1 levels, indicating that HIF1A and hypoxia-induced upregulation of PD-L1 expression constitute a mechanism of tumor cell immune escape." (PMID 35659268, 2022). "We also did not observe a compensation of c-MYC when targeting HIF-1α through USP25, which has previously been linked to HIF activity and shown to be upregulated in a PDAC initiation tumor model with HIF1A deletion." (PMID 35440539, 2022).
tumor (continued). "The heterodimeric (alpha/beta) HIF1A complex binds DNA and induces genes relevant to tumor progression, e.g., those responsible for angiogenesis or metastasis control." (PMID 36230822, 2022). "HIF-1alpha (HIF1A) stimulates the expression and activation of glycolytic isomerase that differs from normal cells, thereby supporting tumor-related metabolism by enhancing macromolecular biosynthesis and energy production pathways in human cancers." (PMID 35721542, 2022). "Noninvasive and convenient methods for assessing HIF-1α expression and accurate assessment of whole-tumor hypoxia would be extremely useful." (PMID 35785202, 2022). "The lncRNA SNHG11 binds to the VHL recognition site on HIF-1α, thereby blocking the interaction of VHL and HIF-1α, preventing its ubiquitination and degradation, and promoting tumor metastasis." (PMID 35392171, 2022). "Under low oxygen conditions, HIF-1α stabilizes and migrates to the nucleus, regulating several genes, including those involved in angiogenesis, tumor proliferation, and apoptosis in cancer and ischemia." (PMID 35453602, 2022). "In turn, citrate treatment suppresses HIF1α stability and glycolysis, which can be a therapeutic strategy to prevent further hypoxic tumor progression and overcome chemotherapy resistance in low-glycolytic HCCs with citrate dependence." (PMID 35884416, 2022). "Here, the tumor suppressor GSK3β phosphorylates HIF-1α at three serine residues within the human HIF-1α N-terminal transactivation domain, which results in the Fbw7 and USP28-mediated HIF-1α ubiquitination and VHL-independent proteasomal degradation." (PMID 36699028, 2022). "Hypoxia leads to the accumulation of hypoxia-inducible factor 1-α (HIF-1α), which promotes further tumor angiogenesis and suppresses T-cell function." (PMID 36081554, 2022). "Critically, we show that NKL cells expressing HIF-1α in hypoxia had a better ability to kill tumor cells after hypoxia exposure." (PMID 34999917, 2022). "In the central regions, HIF-1α was highly expressed in Dox− tumor lysates, whereas it was weakly decreased in the setting of reduced Notch1." (PMID 36183290, 2022). "It is well known that AMPK activation can promote OXPHOS and inhibit glycolysis by down-regulating the function of HIF-1α that can promote glycolysis in tumor cells under hypoxic conditions." (PMID 35101076, 2022). "HIF-1α is a pleiotropic transcription activator, mediating transcription of tumor promoting genes including pro-metastatic genes." (PMID 36344992, 2022). "Normal cells secrete eHsp90α only under stress, such as tissue injury signals, whereas many tumour cells have acquired the ability to constitutively secrete Hsp90α driven by oncogenes, such as overexpressed HIF-1α and mutant p538,24,25." (PMID 35835845, 2022). "Further, the role of hypoxemic conditions and HIF1α in regulating GLUT expression needs a little more attention as HIF1α is the master regulator of tumor metabolism." (PMID 36386187, 2022). "In mice with a conditional HIF-1α KO in NKp46+ cells, tumor-infiltrating NK cells showed increased cytokine production." (PMID 35769460, 2022). "Consistent with prior reports, our study demonstrated higher expression levels of HIF-1α in tumor specimens compared to autologous normal renal tissue." (PMID 36818371, 2022). "The univariate analysis of clinicopathological features revealed that tumor size and HIF-1α-positive expression were significantly different between PTCs with and without capsule invasion (p < 0.05)." (PMID 36329448, 2022). "HIF-1α is generally targeted for ubiquitin-mediated destruction by proline hydroxylation and association with the Von Hippel-Lindau (VHL) tumor suppressor complex under normoxic conditions, but it is stabilised when the partial pressure of oxygen is low." (PMID 35432450, 2022).
tumor (continued). "Activation of the Stat3 signaling pathway leads to the nuclear translocation of Stat3 where it binds to promoter regions of target genes such as Myc, Bcl-2, cyclin D1, VEGF, and HIF-1α, some of which have been related to cell migration and tumor invasion." (PMID 35625843, 2022). "HIF-1α/ERRα interaction promotes the adaptation of tumor cells to hypoxia, suggesting that there is a positive circuit among HIF-1α, ERRα, and mitochondrial biogenesis." (PMID 35800058, 2022). "In tumor tissues with SDH mutations such as paragangliomas and phaeochromocytomas, increased succinate concentrations together with increased expression of HIF1α and associated angiogenic genes such as VEGF were reported." (PMID 36551845, 2022). "For example, hypoxia-inducible factor-1α (HIF-1α) has been proven to play an important role in promoting OC chemoresistance, tumor metastasis, and immunosuppression." (PMID 35418998, 2022). "For ROS staining assay, OFCCF + group showed the strongest DCFH-DA fluorescence signals in tumor slices, which was consistent with the HIF-1α (green) staining assay results." (PMID 35413984, 2022). "There is substantial evidence to suggest that HIF-1α can contribute to abnormalities in the apoptosis machinery, leading to the resistant phenotype of tumor cells in chemo/radiotherapy." (PMID 36551540, 2022). "Unexpectedly, the median level of mRNA expression of HIF1α was high in only 7 tumor tissues (ESCA, GBM, HNSC, LAML, LGG, PAAD, and STAD) compared to normal tissues." (PMID 35860430, 2022). "For instance, Honokiol (HNK), a natural compound, inhibited the glycolysis of BC cells and indirectly blocked tumor growth by targeting HIF-1α/GLUT1/PDK1/HK2 pathway." (PMID 36532768, 2022). "Tumor cells mainly adapt to hypoxic conditions through activation of the transcription factor HIF-1α to alter cell metabolism." (PMID 36140753, 2022). "In contrast, another study demonstrated that hypoxia-inducible factor-1α (HIF-1α) deletion led to the reduction in T cell infiltration and tumor killing during hypoxia conditions." (PMID 36200045, 2022). "Hypoxia inducible factor-1α (HIF-1α) is a key regulator of tumor invasion and a key promoter of energy adaptation." (PMID 35800058, 2022). "In particular, HIF-1α is a key molecule induced under hypoxic conditions during excessive tumor growth and can control the expression of target genes involved in tumor angiogenesis, proliferation, invasion, and metastasis in various cancers." (PMID 36064348, 2022). "Combined inhibition of IGF2BP3 and HIF-1α is reported to further prevent tumor angiogenesis and metastasis." (PMID 35794625, 2022). "Taken together, these observations showed that GSK3α-mediated tumor angiogenesis depends on HIF1α expression." (PMID 35292059, 2022). "The intranuclear expression of HIF-1α in tumor cells was significantly greater in the intraosseous region than in the extraosseous region, which indicated that the intraosseous region was under hypoxic conditions relative to the extraosseous region." (PMID 36669005, 2022). "Cyclin-dependent kinase-1 (CDK1) phosphorylates HIF-1α at serine 668, increasing the expression of HIF-1α and its target genes and boosting tumor angiogenesis, proliferation, and growth." (PMID 36338690, 2022). "We have investigated the ability of metformin and PX-478 to inhibit HIF-1α and suppress PD-L1 expression on tumor cells in recent years." (PMID 35805044, 2022). "This mild hyperthermia can improve oxygen levels and reduce expression of hypoxia-induced factor-1α (HIF-1α) inside tumors, which brings about alleviation of tumor hypoxia and reversion of hypoxia-induced radio-resistance." (PMID 36559162, 2022). "As a consequence, overexpression of hypoxia-inducible factor 1 alpha (HIF1α) is primarily found in tumor cells in proximity to the tumor core." (PMID 35619923, 2022). "On the one hand, this isoform is considered to suppress tumor angiogenesis by repressing proangiogenic and proinflammatory cytokines, as well as HIF1α." (PMID 35867729, 2022).
tumor (continued). "Implantation of HIF-1α silenced A549 cells into nude mice results in reduced lung metastatic nodules accompanied by reversal of E-cadherin and vimentin expression in tumor cells." (PMID 36344992, 2022). "In the present study, we found that tumour microenvironment factors can induce the stabilization of HIF‐1α and increase the expression of FOXM1 in NPC cells under hypoxic and normoxic conditions." (PMID 35656815, 2022). "A wealth of reports based on immunohistochemical studies of human tumor sections indicate that HIF-1α is overexpressed in the majority of human cancers and these elevated levels correlate with cancer-related death." (PMID 35158767, 2022). "On the other hand, magnolol also acted as an important role in tumor cells through reducing hypoxia /HIF-1α-mediated VEGF secretion." (PMID 36234977, 2022). "The expression of p-Src and HIF-1α in persistent tumor cells increased and was dependent on EGFR-TKI treatment." (PMID 36612121, 2022). "Specifically, HIF-1α expression was observed to be highly upregulated in TNBCs to withstand a hypoxic tumor microenvironment." (PMID 36012111, 2022). "Recently, growing evidence has revealed that HIF-1α participates in multiple processes of hypoxic tumor cells and acts as an essential transcription factor induced by hypoxia." (PMID 35764883, 2022). "Results also showed that TRAP1-expressing tumor cells have a high level of succinate, resulting in HIF-1α stabilization." (PMID 35127545, 2022). "PI3K signaling pathway plays a key role in tumor angiogenesis by regulating the expression of HIF-1α and VEGF." (PMID 35903690, 2022). "For instance, ALDH1A1 has been shown to promote tumor angiogenesis via retinoic acid/HIF-1α/VEGF signaling in MCF-7 breast cancer cells." (PMID 36347835, 2022). "Among the altered factors in HCC, hypoxia-inducible factor 1-alpha (HIF-1α) is overexpressed in this type of tumor and is related to its severity." (PMID 35457229, 2022). "The in vivo tumor hypoxia will be evaluated via immunohistochemistry of HIF-1α or pimonidazole staining to demonstrate hypoxia recovery after OMB treatment." (PMID 35631488, 2022). "HIF-1α regulates the expression of additional genes that promote tumor progression including vascular endothelial growth factor (VEGF), which is a pro-angiogenic factor that promotes neovascularization." (PMID 36230617, 2022). "These collective results support the emerging role of HIF-1α in promoting DNA repair and chemo/radioresistance in a range of tumor cells." (PMID 36551540, 2022). "Others have found that inhibition of the HIF-1α pathway improves the anti-tumor effect of 5-FU, and improves ICB responses in preclinical models." (PMID 35634282, 2022). "The use of HIF-1α inhibitors can attenuate tumor EMT, migration, invasion, and metastasis by blocking the regulatory effects of HIF-1α on EMT-TFs and HIFAL." (PMID 36139386, 2022). "Some studies have found Sept9 to be a key factor for the binding and stabilization of Hif-1α and that it can increase the transcription of Hif-1α and activate Sept9-Hif-1α, thereby forming blood vessels and promoting tumor growth." (PMID 35096204, 2022). "Higher levels of lactate within the tumor site have been recognized to upregulate the expression of HIF-1α, which promotes the expression levels of VEGFA responsible for increased angiogenesis." (PMID 35008414, 2022). "It is only when the oxygen concentration reaches <5% (such as when the volume of the tumor has grown to >300 mm2) that HIF-1α can exist stably." (PMID 36555795, 2022). "HIF-1α cross-talk with HIF-2α maintains a balanced state of tumor cells’ demand for hypoxic factors." (PMID 35935986, 2022). "The tumor survival is mediated by HIF-1α in a hypoxic environment through inhibition of MYC, a transcriptional factor regulating mitochondrial mass and oxygen consumption in several human cancers." (PMID 35798726, 2022).